BRAF (B-Raf proto-oncogene, serine/threonine kinase)
Diseases named in the same sentence as BRAF in open-access papers (continued):
Sharing a sentence is not in itself a finding about the gene and the disease.
follicular thyroid carcinoma (61 papers, 2006 to 2025). "The most common genetic mutations in papillary and follicular thyroid cancers are point mutations of the BRAF or RAS genes, while the most common chromosomal alterations are RET/PTC and PAX8/PPARγ rearrangements." (PMID 29721199, 2018). "For example, RAS mutation in follicular thyroid carcinoma was more common than BRAF." (PMID 35992139, 2022). "However, the presence of a BRAF mutation (T1799A: V600E) in WRO questions the use of this cell line as a model for follicular thyroid carcinoma (FTC)." (PMID 23162534, 2012). "There are other mutations of the BRAF gene, such as K601E, which displays lower oncogenic activity in vitro than V600E; indeed, the kinase activity of V600E is 2.5 times greater than that of the K601E that has been identified in follicular adenomas and, more rarely, in some follicular carcinomas." (PMID 26693224, 2015). "This divergence underscores a critical diagnostic limitation of a BRAF-only approach, which will inevitably miss a significant proportion of FVPTCs and other RAS-driven entities like follicular thyroid carcinoma (FTC)." (PMID 41551157, 2025). "Patient FNA-0330, who has three mutations (BRAF V600E/NRAS Q61R/AKT1), was confirmed as follicular thyroid carcinoma (FTC) with lymph node metastasis." (PMID 40586006, 2025). "From the BRAF cohort, all operated BRAF positive patients were diagnosed with papillary and follicular carcinoma." (PMID 39001288, 2024). "BRAF p.K601E has been reported in a few cases of follicular thyroid carcinoma, as well as in one case of NIFTP and four cases of follicular adenoma." (PMID 36835466, 2023). "Out of the 14 BRAF-positive cases, five were follicular neoplasms, with the latter category comprising three cases of follicular adenomas and two of follicular carcinomas." (PMID 34345541, 2021). "An association between the type of mutation (BRAF or RAS) and the metastasis pathway typical for papillary and follicular thyroid cancer (lymphogenic or hematogenic) has also been described." (PMID 34630336, 2021). "Both the follicular thyroid carcinoma (FTC) and the metastasis were investigated for the presence of BRAF/RAS and TERT promoter mutations." (PMID 31417495, 2019). "Four molecular alterations, BRAF and RAS point mutations, and RET/PTC and PAX8/PPARγ rearrangements, are the most frequent causes of thyroid papillary and follicular carcinomas." (PMID 29721199, 2018). "The BRAF V600E mutation occurs in 45–80% of sporadic PTC cases but never in either benign lesions such as follicular adenomas, and nodular goiters, or follicular thyroid carcinoma (FTC)." (PMID 29132392, 2017). "The presence of BRAF V600E mutation confers >99% risk of malignancy, yet its application is limited due to its low prevalence in follicular variants of PTC and follicular carcinomas." (PMID 23049733, 2012). "Confirmatory Sanger sequencing unveiled a novel sequence variation involving nucleotide duplication within the range of 1794 to 1802, a non-V600E BRAF mutation not previously reported in follicular thyroid carcinoma." (PMID 39288226, 2024). "BRAF mutation was as high as 79.8% in PTC, whereas it was 50.0% in follicular thyroid carcinoma." (PMID 38734621, 2024). "In line with this, Ciampi, Zhu, and Nikiforov reported that BRAF copy number gain was associated with more invasive follicular thyroid carcinomas compared to tumors with no copy number change." (PMID 38919805, 2024). "BRAF mutations are rare in follicular thyroid carcinoma (1.4%), and they do not seem to exist in benign nodules." (PMID 37374164, 2023). "We observed that KRAS mutation occurred in 41.3% of the BRAF negative thyroid cancer samples, and 52.6% of it was found in follicular thyroid carcinoma." (PMID 36510281, 2022).
follicular thyroid carcinoma (continued). "In normal thyroid cells, E-cadherin is expressed in the basolateral membrane and its downregulation, by activation of oncogenes such as BRAF, has been implicated in the induction of the epithelial mesenchymal transition (EMT) in follicular thyroid cancer cells." (PMID 34794464, 2021). "When medullary and follicular thyroid carcinoma cases were excluded, the sensitivity, specificity, positive and negative predictive values, and accuracy of BRAF mutation analysis were 83.2%, 98.0%, 97.5%, 86.2%, and 90.9%, respectively." (PMID 30118506, 2018). "In the benign cytology group (n = 87), 2 benign nodules (1 nodular hyperplasia and 1 non-surgical benign nodule) were false positive and 3 malignant nodules (2 PTCs and 1 follicular thyroid carcinoma) were false negative on BRAF mutation analysis." (PMID 30118506, 2018). "Follicular carcinomas are not susceptible to BRAF mutation; therefore, PDTCs arising from FTCs must be BRAF-mutation-negative." (PMID 23476646, 2013). "The BRAF V600E mutation is not found in follicular thyroid cancers and benign thyroid nodules." (PMID 34345541, 2021). "In the benign cytology group (Bethesda category I or II, n = 104), 4 malignant nodules were negative on BRAF mutation analysis (3 PTCs and 1 follicular thyroid carcinoma) and 2 benign nodules were positive on BRAF mutation analysis (1 nodular hyperplasia and 1 non-surgical benign nodule)." (PMID 30118506, 2018). "However, current published reports include no data directly comparing cell lines with and without BRAF mutations or describing the effects of sorafenib in cell lines derived from follicular thyroid carcinomas (FTC)." (PMID 25879531, 2015). "Interestingly, none of the 14 follicular adenomas and 3 follicular carcinomas showed BRAF V600E mutation." (PMID 24252159, 2013). "In addition, none of the 14 follicular adenomas and 3 follicular carcinomas had BRAF V600E mutation." (PMID 24252159, 2013). "For follicular thyroid carcinoma (FTC), cases positive for BRAF V600E had thyroglobulin levels similar to those observed in PTC (28.5 ± 14.0 ng/mL)." (PMID 39767732, 2024). "Cell lines from follicular carcinomas, with exception of the relatively insensitive FTC238 cells, had midrange IC50 values suggesting that sorafenib targets kinases other than BRAF in these cells." (PMID 25879531, 2015). "In agreement with the previous study, BRAF mutation has been reported in 30-80% of PTC, and also in AC which develops from pre-existing PTC, but is never detected in follicular carcinoma or benign nodules." (PMID 33247684, 2020). "Two malignant thyroid nodules with indeterminate US diagnoses and negative BRAF mutation analysis were diagnosed as PTC and follicular thyroid carcinoma after thyroid surgery, respectively." (PMID 30118506, 2018). "In our recent study, we found no statistical significance in the prevalence of BRAF V600E, RET/PTC rearrangements or RAS mutations in papillary and follicular thyroid carcinomas from an iodine-rich country (Japan) and an iodine-deficient country (Vietnam)." (PMID 27793009, 2017). "There were no cases positive for BRAF in follicular carcinomas (FTCs), Hürthle cell carcinomas (HCCs) or medullary thyroid carcinomas (MTCs)." (PMID 23946802, 2013). "Nevertheless, RAS or RAS‐like mutations (e.g. BRAF K601E) are not specifically associated with malignancy and are usually detected in follicular‐patterned neoplasms, which commonly include follicular adenoma, NIFTP, follicular variant PTC and follicular carcinoma." (PMID 35247035, 2022).
ameloblastoma (60 papers, 2015 to 2026). The most common odontogenic tumor, arising from the epithelial component of the embryonic tooth and usually affecting the molar-ramus region of the mandible or maxilla. "A molecularly targeted approach has been proposed for ameloblastoma treatment as the BRAF V600E mutation has been found in 2/3 of cases of such tumors." (PMID 41144131, 2025). "In vitro experiments demonstrated that BRAF-mutated ameloblastoma cells exhibited the constitutive activation of the MAPK pathway, which was inhibited by the BRAF inhibitor vemurafenib." (PMID 40699660, 2025). "BRAF p.V600E mutations, the most common activating mutation in conventional ameloblastoma, have been identified in AC, but their diagnostic value remains uncertain." (PMID 40699660, 2025). "In contrast, the tumor cohort in this study excluded ameloblastomas, which are characterized by a particularly high prevalence of BRAF mutations." (PMID 41364259, 2025). "Some recent studies in ameloblastoma indicate that BRAF mutations are frequently identified, particularly the BRAF V600E mutation, in some aggressive varieties of ameloblastoma." (PMID 41185044, 2025). "In particular, BRAF p.V600E is strongly associated with ameloblastomas, while PTCH1 mutations predominate in odontogenic keratocysts." (PMID 41364259, 2025). "In modern animals, mutations in this pathway—especially the BRAF V600E mutation—are frequently associated with ameloblastomas, a type of tumor that typically originates in the mandible." (PMID 40282235, 2025). "Among these, the BRAF V600E mutation is the most prevalent, reported in approximately 62% of ameloblastomas, with a higher frequency in mandibular lesions." (PMID 41030734, 2025). "One recent report also described the use of the PI3K inhibitor Copanlisib in a patient with metastasizing ameloblastoma with a PI3K mutation (on a BRAF mutated background)." (PMID 41144131, 2025). "In that study, mandibular ameloblastomas predominantly harbored BRAF p.V600E mutations, while maxillary counterparts often carried SMO alterations." (PMID 41364259, 2025). "One of the most significant developments in the understanding of ameloblastoma at the molecular level is the identification of mutations in the BRAF gene." (PMID 39274556, 2024). "It is imperative to delve deeper into research by assessing the outcomes of targeted therapies for BRAF inhibition in cases of mutated ameloblastomas." (PMID 38615253, 2024). "Autophagy has been recently shown to occur in ameloblastomas, raising the possibility of a sequence of events comprised of BRAF mutation/BRAFi leading to senescence (p16 expression), autophagy, and squamous differentiation." (PMID 39621130, 2024). "Overall, it is estimated that 80–90% of all subtypes of ameloblastoma are associated with the BRAF V600E mutation." (PMID 39597858, 2024). "Through immunohistochemical analysis, this study revealed a substantial percentage of 75.6% of ameloblastomas harboring mutations in BRAF V600E, with the highest significance observed in unicystic cases, where 90% of them tested positive for this mutation." (PMID 38615253, 2024). "The present study aimed to provide a novel description and measurable assessment of the histomorphologic modifications and selective molecular changes in BRAF-mutated, target-treated ameloblastomas." (PMID 39621130, 2024). "A deeper understanding of the condition has emerged, primarily due to the identification of the BRAF V600E mutation, which is present in around 70% of ameloblastoma cases." (PMID 38615253, 2024). "Recent studies have identified the BRAF V600E mutation in 63 % of ameloblastoma lesions, leading to the use of the molecular-targeted drug dabrafenib." (PMID 39654782, 2024). "Investigations into BRAF V600E mutations in ameloblastomas have been conducted in different previous studies; however, as of our current understanding, no analogous investigation specifically focused on Latin American cases has been undertaken." (PMID 38615253, 2024).
ameloblastoma (continued). "Food and Drug Administration (FDA)-approved molecular targeted therapy for ameloblastomas include drugs able to inhibit the functions of mutated BRAF and mitogen-activated protein kinase kinase (MEK)." (PMID 39597858, 2024). "On the other hand, in Sweeney's traditional study, a correlation is demonstrated with the histological pattern of ameloblastomas, where most cases of follicular or desmoplastic ameloblastomas exhibited mutations in either SMO or BRAF genes." (PMID 38615253, 2024). "BRAF-mutated ameloblastomas can be targeted by BRAF inhibitors to markedly reduce their size, enabling conservative removal of residual tumor." (PMID 39621130, 2024). "While malignant tumors carry several critical mutations that lead to high proliferation when in combination, ameloblastomas are heavily reliant upon the driver BRAF mutation that is associated with low proliferation rates." (PMID 39621130, 2024). "In this context, this is the first multi-institutional study evaluating the landscape related to the BRAF V600E mutation in a substantial sample of ameloblastomas diagnosed in Latin America." (PMID 38615253, 2024). "The BRAF V600E mutation, which is common in various cancers, has been detected in a significant proportion of ameloblastoma cases." (PMID 39274556, 2024). "In this study, potential relationships between the histological subtypes of ameloblastomas and BRAF V600E mutation were evaluated." (PMID 38615253, 2024). "The literature review on the four databases yielded 264 results, from which the 10 largest case series investigating BRAF V600E mutation through immunohistochemistry in ameloblastomas were selected." (PMID 38615253, 2024). "It has been demonstrated that there is a predominance of mandibular and younger occurring ameloblastomas exhibiting BRAF mutations and some studies have shown an association between this mutation and tumor aggressiveness." (PMID 38615253, 2024). "On the contrary, other factors, such as sex, histological variants, and recurrence, were insignificant among ameloblastoma cases with the BRAF V600E mutation." (PMID 39274556, 2024). "As research into the BRAF-V600E gene mutation continues, the use of targeted therapeutic agents for this mutation in ameloblastoma is expected to become a valuable adjuvant treatment to reduce the recurrence rate of patients." (PMID 37646022, 2023). "BRAF V600E is a specific mutation of the BRAF gene that has been extensively studied in various neoplasms, including ameloblastoma, unicystic ameloblastoma, acanthomatous ameloblastoma, plexiform ameloblastoma, and metastatic ameloblastoma." (PMID 38021761, 2023). "The presence of the BRAF mutation is also linked to clinical behavior in ameloblastomas, often being associated with other mutations and occurring more frequently in younger patients." (PMID 38021761, 2023). "The BRAF-V600E gene mutation has been identified as a crucial factor in the pathogenesis of ameloblastoma." (PMID 37646022, 2023). "Overall, the BRAF V600E mutation has emerged as a predictive, diagnostic, and prognostic biomarker in ameloblastomas." (PMID 38021761, 2023). "The MAPK/ERK pathway has been found to be activated by the BRAF-V600E gene mutation, leading to increased cell proliferation and inhibition of apoptosis and promoting the development of ameloblastoma." (PMID 37646022, 2023). "This study will employ five ML algorithms based on CT and combine radiomics and clinical features of patients to evaluate the model’s effectiveness in predicting BRAF-V600E gene mutations in ameloblastoma." (PMID 37646022, 2023). "We included clinical information such as age, gender, tumor location, and tumor diameter of patients with ameloblastoma to establish a correlation between this clinical information and the BRAF-V600E gene mutation." (PMID 37646022, 2023). "The prevalence of BRAF-V600E gene mutation in aggressive and recurrent ameloblastoma suggests a potential role in the biological behavior of the tumor." (PMID 37646022, 2023).
ameloblastoma (continued). "The BRAF V600E mutation in ameloblastomas is more frequent in the mandible, particularly in the body, ramus, and symphysis." (PMID 38021761, 2023). "Meanwhile, it has been found that ameloblastoma carrying mutations in the BRAF gene tend to occur more frequently in the mandible and in younger patients." (PMID 37646022, 2023). "Metastatic ameloblastoma, a rare ameloblastoma that develops metastases despite its benign appearance, was found to have a higher prevalence of BRAF V600E mutations compared to other ameloblastomas." (PMID 38021761, 2023). "One of the most prevalent mutations identified in ameloblastoma is the BRAF proto-oncogene serine/threonine kinase (BRAF) V600E mutation, and targeted treatment strategies against this mutation have shown promising outcomes." (PMID 38021761, 2023). "In conclusion, this study demonstrated that a combination of radiomics signatures and clinical features can accurately predict BRAF-V600E gene mutation status in patients with ameloblastoma." (PMID 37646022, 2023). "In the case of ameloblastoma, the BRAF V600E mutation has emerged as a potential therapeutic target." (PMID 38021761, 2023). "The objective of this study is to develop and validate a radiomics-based machine learning method for the identification of BRAF-V600E gene mutations in ameloblastoma patients." (PMID 37646022, 2023). "Ameloblastoma in 66% of the cases harbor a somatic mutation of the “mitogen-activated protein kinase” signaling pathway (BRAF V600E)." (PMID 37115331, 2023). "In vitro studies have shown promising results for the therapeutic use of treatments targeting the BRAF V600E mutation in ameloblastomas." (PMID 38021761, 2023). "Our study presents a comprehensive radiomics-based machine learning model using five different methods to accurately detect BRAF-V600E gene mutations in patients diagnosed with ameloblastoma." (PMID 37646022, 2023). "While some studies have explored the relationship between radiomics features and BRAF gene mutation status, the role of CT-based machine learning (ML) for radiomics in identifying BRAF-V600E gene mutations in ameloblastoma remains to be investigated." (PMID 37646022, 2023). "In this article, we review the presence of BRAF V600E mutations, their inhibitors, and targeted therapies in ameloblastoma." (PMID 38021761, 2023). "In the treatment of ameloblastomas, the identification of BRAF V600E and additional mutations as the prime targeted therapies has proven to be a significant breakthrough where surgical treatment was contraindicated." (PMID 38021761, 2023). "In this retrospective study, data from 103 patients diagnosed with ameloblastoma who underwent BRAF-V600E mutation testing were collected." (PMID 37646022, 2023). "In this study, we propose a predictive model based on a combination of non-invasive CT images and patient clinical features to predict BRAF-V600E gene mutation status in patients with ameloblastoma." (PMID 37646022, 2023). "Considering the fact that depending on the study, on average 2/3 of ameloblastoma show the BRAF-V600E mutation and that the standard therapy currently does not include a standardized drug therapy, and the data of the case reports cannot be given enough value." (PMID 37115331, 2023). "Acanthomatous ameloblastoma, classified as an aggressive ameloblastic tumor with a tendency to metastasize, has also been found to harbor BRAF mutations similar to ameloblastoma." (PMID 38021761, 2023). "As a result of the significant outcome of BRAF V600E mutation in ameloblastoma pathogenesis, targeted therapy formulation can be developed with this handful of evidence." (PMID 36428683, 2022). "Meta-analysis prevalence of BRAF V600E in ameloblastoma was 70.49%, and a significant meta-analysis association was reported for those younger than 54 years old and in the mandible." (PMID 36428683, 2022).